SIRT1 (sirtuin 1)
Diseases named in the same sentence as SIRT1 in open-access papers (continued):
Sharing a sentence is not in itself a finding about the gene and the disease.
energy metabolism disorder (3 papers, 2021 to 2025). "BYHWD improved cerebral energy metabolic disorders by activating the SIRT1/AMPK signaling pathway, thereby enhancing glycolytic capacity and TCA cycle capacity." (PMID 40624684, 2025). "The effect of DR was attributable to its two components, with DLA binding to Sirt-1 to regulate the activity of Complex I as an antioxidant, while R1 regulating ATP 5D expression to enhance the activity of Complex V to attenuate energy metabolism disorder." (PMID 34322032, 2021). "Graphene-FIR therapy activated the thermogenic program in adipose tissue, increasing the expression of UCP1 and GLUT4, activating the AMPK/PGC-1α/SIRT1 pathway in BAT and iWAT, and improving energy metabolism disorder in HFD mice." (PMID 40076847, 2025). "Further, graphene-FIR therapy activated the thermogenic program in adipose tissue, increasing the expression of UCP1 and glucose transporter protein four (GLUT4), activating the AMPK/PGC-1α/SIRT1 pathway in iWAT and BAT, and improving energy metabolism disorder in HFD mice." (PMID 40076847, 2025). "The therapy activated the AMPK/PGC-1α/SIRT1 pathway in adipose tissue, increasing the expression of uncoupling protein 1 (UCP1) and glucose transporter protein four (GLUT4), activating the thermogenic program in adipose tissue, and improving energy metabolism disorder in HFD mice." (PMID 40076847, 2025).
gallstones (3 papers, 2016 to 2025). Solid crystalline precipitates in the biliary tract, usually formed in the gallbladder, resulting in the condition of cholelithiasis. "Intriguingly, prior research has suggested the role of the AMPK/SIRT1 signaling pathway in gallstone formation." (PMID 37641009, 2023). "In addition, hepatic deprivation of SIRT1 was unfolded to induce cholesterol gallstone formation in a mouse model." (PMID 37641009, 2023). "Related studies on the synthesis of cholesterol and human gallstones have shown that the FXR/SHP pathway regulates the miR-34a expression and its target SIRT1, which is associated with gallstones because it participates in lipid metabolism and hepatic bile acid synthesis." (PMID 27223281, 2016). "Overexpression of AQP3 activated the AMPK (adenosine monophosphate-activated protein kinase) / SIRT1 (sirtuin-1) signaling pathway to reduce LPS-induced inflammatory injury of the gallbladder mucosa epithelium, thereby ameliorating gallbladder damage and repressing gallstone formation in mice." (PMID 37641009, 2023). "In addition, hepatic deprivation of SIRT1 could contribute to cholesterol gallstone formation in mice by decreasing hepatocyte nuclear factor 1α/farnesoid X receptor signaling." (PMID 37641009, 2023). "Data from our study highlight the inhibitory role of AQP3 in gallbladder damage and gallstone formation in mice by reducing inflammatory injury of gallbladder mucosal epithelial cells, which is achieved through activation of the AMPK/SIRT1 signaling pathway." (PMID 37641009, 2023).
gastric ulcer (3 papers, 2024 to 2025). An ulcerated lesion in the mucosal surface of the stomach. "This study aims to evaluate the gastroprotective effects of free hesperidin and its chitosan nanoparticles (HNPs) against ethanol-induced gastric ulcers in rats, focusing on the Sirt-1/FOXO1/PGC-1α/HO-1 signaling pathway." (PMID 39314751, 2024). "Moreover, the sustained release profile of OMP-NS may provide a continuous therapeutic effect, promoting prolonged activation of Nrf2, PPAR-γ, and SIRT-1, which are crucial for the healing of gastric ulcers." (PMID 40563542, 2025). "Taken together, SIRT1 may be an appealing protective and therapeutic target against gastric ulcers." (PMID 38441571, 2024).
growth disorders (3 papers, 2023 to 2024). "Therefore, the assessment of the SIRT1 concentration in short-stature children seems interesting, as changes in its concentration may play an important role in growth disorders in children—being the cause or effect of certain abnormalities or adaptation mechanism." (PMID 39062007, 2024). "However, taking into account data from the literature, further investigation regarding SIRT1 involvement in growth disorders as well as weight and pubertal disturbances is warranted." (PMID 38529393, 2024). "Considering that SIRT1 activity can be modulated by various factors, it should be noted that sirtuin triggers and inhibitors may be utilized in the future to develop new treatments for children with growth disorders." (PMID 37895086, 2023). "Thus, it seems that SIRT1 may play a role in growth disorders in children." (PMID 39062007, 2024).
gynecologic cancer (3 papers, 2020 to 2025). "SIRT1 has been shown to be upregulated in multiple tumor types, including gynecologic cancers, suggesting a strong association of its expression to tumorigenesis." (PMID 39272943, 2024). "While several SIRT1 inhibitors have shown promise in preclinical studies for breast and gynecological cancers, clinical trials specifically targeting these malignancies remain limited." (PMID 41300302, 2025). "In breast and gynecologic cancers, SIRT1 exhibits context-dependent roles, functioning as either a tumor suppressor or tumor promoter depending on the cellular environment and cancer subtype." (PMID 41300302, 2025). "In the past five years, there have been no large, fully randomized oncology trials specifically testing selective SIRT1 inhibitors or activators in breast or gynecologic cancers." (PMID 41300302, 2025). "Below is an overview of notable SIRT1 inhibitors and their relevance to breast and gynecological cancers." (PMID 41300302, 2025). "In certain gynecological cancers, SIRT1 deacetylated both FOXO1 and FOXO3a, reducing their pro-apoptotic and anti-proliferative effects and increasing proliferation and survival." (PMID 41300302, 2025). "Below, we outline how SIRT1 functions in gynecologic cancers, including its potential role in cancer development, progression, and therapy." (PMID 41300302, 2025). "Across gynecologic cancers, SIRT1 expression was shown to have high heterogeneity across histological subtypes, making characterizing its role difficult." (PMID 39272943, 2024). "Overcoming these hurdles will require the development of more selective and potent compounds, improved patient stratification using molecular markers, and well-designed, longer-term clinical studies to fully realize the potential of SIRT1-targeted therapies in breast and gynecologic cancers." (PMID 41300302, 2025). "SIRT1 regulation of FOXO transcription factors plays a complex and context-dependent role in breast and gynecological cancers (ovarian, endometrial, cervical)." (PMID 41300302, 2025). "Sirtuin 1 (SIRT1), an NAD+-dependent histone deacetylase, exerts complex and context-dependent effects in breast and gynecological cancers." (PMID 41300302, 2025).
hyperuricemia (3 papers, 2021 to 2023). An abnormally high level of uric acid. "Interestingly, elevated estrogen levels caused by SIRT1 may also be responsible for treatment of hyperuricemia." (PMID 36632457, 2023). "Polydatin has also been shown to inhibit NF-κB/NLRP3 through the AMPK/SIRT1 pathway, thereby reducing potassium oxonate-induced hyperuricemia and renal inflammation." (PMID 36632457, 2023). "In the mouse with hyperuricemia, the expression of ATP-binding cassette subfamily G member 2 in ileum was activated by acetylation PGC-1α/PPARγ pathway after SIRT1 activation by Res, reducing the level of serum uric acid, thus exerting an anti-hyperuricemia effect." (PMID 36632457, 2023). "In conclusion, these studies suggest that SIRT1 may be a potential target of hyperuricemia and its complications, which is of great significance for further clinical research and application." (PMID 36632457, 2023). "The core targets of Plantaginis Herba for the treatment of hyperuricemia were AKT1, mitogen-activated protein kinase 3 (MAPK3), MAPK1, tumor necrosis factor (TNF), prostaglandin-endoperoxide synthase 2 (PTGS2), sirtuin 1 (SIRT1), estrogen receptor 1 (ESR1), and androgen receptor (AR)." (PMID 33897800, 2021).
IgA nephropathy (3 papers, 2020 to 2022). "We also examined intra-renal expression levels of Sirt1, Sirt3, Sirt6, and Nmnat1 in specimens from patients with IgA nephropathy." (PMID 35962139, 2022). "Intra-renal expression levels of Sirt1, Sirt3, Sirt6, and Nmnat1 were evaluated in specimens from 27 patients who were histologically diagnosed with FSGS and IgA nephropathy." (PMID 35962139, 2022).
ischemic disease (3 papers, 2016 to 2025). Lack of blood supply to an area of the body, resulting in impairment of tissue oxygenation. "There is increasing evidence that SIRT1 mediates protein posttranslational modification related to aging and ischemic disease." (PMID 28003866, 2016). "Additionally, a study on the treatment of ischemic diseases found that hsa_circ_0093884 in exosomes derived from endothelial progenitor cells could promote therapeutic neovascularization through the miR-145/SIRT1 pathway." (PMID 41584514, 2025).
joint disease (3 papers, 2021 to 2024). "SIRT1 knockout in chondrocytes led to accelerated development of OA in surgically-induced joint instability in mice." (PMID 37047494, 2023). "Additionally, genetic or pharmacologic activation of SIRT1 reverses deleterious effects of joint disease." (PMID 37047494, 2023).
keloid (3 papers, 2020 to 2024). An irregularly shaped, elevated mark on the skin caused by deposits of excessive amounts of collagen during wound healing. "Herein, we aim to investigate the role and mechanism of SIRT1/EZH2/RUNX3 in abnormal proliferation of benign keloids." (PMID 36476345, 2022). "Herein, we investigated the mechanism of abnormal proliferation in keloids involving Sirtuin 1(SIRT1)/ Zeste Homolog 2 (EZH2)/ Runt-related transcription factor 3 (RUNX3)." (PMID 36476345, 2022). "In keloids, SIRT1 can exacerbate cell death by affecting the SIRT3-SOD2-mROS-dependent autophagy pathway corresponding to 5-ALA-PDT." (PMID 36476345, 2022). "MSC soluble factors can attenuate scar formation by inhibiting protein expression of heat shock factor (HSF)-derived nuclear factor kappa B (NF-κB), alpha-smooth muscle actin through the delivery of miR-138-5p to target Sirtuin-1 (SIRT1) and promoting apoptosis of keloid fibroblasts." (PMID 39185045, 2024). "In summary, our study shows that SIRT1 could promote proliferation by reducing RUNX3 expression in keloids through deacetylation of EZH2." (PMID 36476345, 2022). "The mechanism of cell proliferation involving SIRT1/EZH2/RUNX3 in benign keloids is still unclear." (PMID 36476345, 2022). "Conclusively, the SIRT1/EZH2/RUNX3 axis may be an important pathway in the regulation of abnormal proliferation in keloids." (PMID 36476345, 2022). "SIRT1/EZH2/RUNX3 axis may be important for regulating abnormal proliferation in keloids." (PMID 36476345, 2022). "Considering that RUNX3 may act at tumor suppressor gene in keloids, we analyzed the correlation of SIRT1, EZH2, and RUNX3 expression in keloid tissues and found that there were negative regulatory relationships between SIRT1 and EZH2, and between EZH2 and RUNX3." (PMID 36476345, 2022). "The results showed that the expression levels of SIRT1 (P < 0.05) and RUNX3 (P < 0.05) in keloid tissues were significantly lower than those in normal adjacent skin tissues." (PMID 36476345, 2022). "The expression levels of SIRT1, EZH2 and RUNX3 in keloid specimens and their normal adjacent tissues were detected by Western blot." (PMID 36476345, 2022). "Similar results of SIRT1, EZH2 and RUNX3 were also observed in keloid fibroblasts and normal fibroblasts." (PMID 36476345, 2022). "The proliferation of keloid fibroblasts treated with EX527 was inhibited, and the S and G2 phases of the cell cycle were shortened according to cell cycle analysis (P < 0.01), indicating that SIRT1 can regulate the cell cycle, and the same situation was observed after siEZH2 transfection." (PMID 36476345, 2022).
kidney inflammation (3 papers, 2014 to 2023). "SIRT1-deficient mice have elevated kidney inflammation and urinary albumin excretion." (PMID 30641941, 2019). "SIRT1 overexpression significantly suppressed F4/80, and SRT1720 treatment reduced MCP-1, TNFα, and F4/80 in the offspring exposed to maternal HFD, suggesting the anti-inflammatory effects of SIRT1 against maternal obesity-induced kidney inflammation." (PMID 30641941, 2019).
lentivirus infection (3 papers, 2016 to 2023). Virus diseases caused by the Lentivirus genus. "We found that the mRNA expression of ERβ and SIRT1 in EPCs did not change in Young and Old mice, and interestingly, the lentivirus infection did not affect the gene expression at all." (PMID 27470296, 2016).
leukocytosis (3 papers, 2012 to 2020). "Furthermore, cardiac-restricted mIGF-1 transgene induced systemic changes in a SIRT1-dependent manner, such as high blood pressure, leukocytosis, and an enhanced fear response." (PMID 32901689, 2020).
lipodystrophy (3 papers, 2016 to 2022). A congenital or acquired disorder characterized by abnormal loss or redistribution of the adipose tissue in the body. "Comparison of genotype frequencies of rs2273773, rs7895833, rs12049646, rs12413112 genetics variants in SIRT1 among lipodystrophy subtypes." (PMID 32106282, 2020). "Our results do not support these findings in HIV-infected individuals and suggest that the SIRT1 gene may not be involved in the etiology of lipodystrophy in these patients." (PMID 32106282, 2020).
Machado-Joseph disease (3 papers, 2018 to 2022). "CR was found to increase SIRT1 levels in the brains of Machado-Joseph disease (MJD) mice, significantly improve neuropathology, reduce neuroinflammation and activate autophagy." (PMID 36712965, 2022). "For example, in a SCA-3 (Machado-Joseph disease, MJD) mouse model, resveratrol activates the histone deacetylase enzyme SIRT1 pathway, showing improvement in motor behavior when treating animals at a post-symptomatic stage of disease development." (PMID 30544977, 2018). "In Machado-Joseph disease (MJD), a neurodegenerative disease with an abnormal expansion of the CAG triplet in the ATXN3 gene, resveratrol elevated the SIRT1 expression to improve motor deficits." (PMID 33809718, 2021).
meningioma (3 papers, 2016 to 2025). A generally slow growing tumor attached to the dura mater. "By targeting the SULT1E1+ subpopulation, we identified SRT1720, an SIRT1 agonist, as a potential systemic treatment and radiation sensitizer for high‐grade meningiomas." (PMID 36994665, 2023).
mental disorder (3 papers, 2017 to 2025). A disease that has its basis in the disruption of mental process. "While the concept of heterozygote advantage is still an active area of research and debate in genetics, and its role in mental disorders is not yet fully established, our findings suggest that the SIRT1 gene may play a protective role in depressive symptoms." (PMID 37124257, 2023).
metastatic tumors (3 papers, 2013 to 2022). "SIRT1 is under investigation as a therapeutic target in metabolic, cardiovascular, neurodegenerative and metastatic diseases." (PMID 24386389, 2013). "The mRNA (messenger ribonucleic acid) expression levels of SIRT1, FoxO1 and FoxO3a were significantly decreased in 4TLM metastatic tumors compared to 67NR non-metastatic tumors, whereas the FoxO4 signal was significantly increased in metastatic tumors (p ˂ 0.05)." (PMID 36142156, 2022).
migraine (3 papers, 2021 to 2025). "Therefore, SIRT1 may be a pharmacological target of ligustrazine, which reduces migraine-associated neuroinflammation and oxidative stress by interfering with the crosstalk between microglia and neurons." (PMID 40724883, 2025). "Overall, the development of migraine may be associated with downregulated levels of SIRT1." (PMID 40724883, 2025). "There is no direct evidence regarding the involvement of sirtuins other than SIRT1 or SIRT2 in migraine, but reports on the role of other sirtuins in neurological disorders justify further research on this subject." (PMID 40724883, 2025). "SIRT1 has also been shown to support migraine therapy with ligustrazine, the main component of the traditional edible-medicinal herb Ligusticum chuanxiong Hort., which is characterized by numerous clinical effects, including the expansion of small arteries." (PMID 40724883, 2025). "The protective role of SIRT1 in migraine was demonstrated in a study in which miRNA-155-5p was found to promote neuroinflammation and central sensitization in the trigeminal nucleus caudalis of a nitroglycerin-induced mouse model of CM." (PMID 40724883, 2025). "Because miR‐34a‐5p was shown to be up‐regulated in patients with migraine, we down‐regulated miR‐34a‐5p by using its inhibitor, and then we detected the expression level of SIRT1, IL‐1β, miR‐34a‐5p, NF‐κB p65 and COX2 by quantitative real‐time PCR." (PMID 33155431, 2021). "Therefore, SIRT1 may exert a protective effect in migraine by improving mitochondrial functions." (PMID 40724883, 2025). "It’s confirmed that upregulating Sirt1, another Sirt family member, alleviated mitochondrial dysfunction in TNC of migraine rat models." (PMID 37271805, 2023). "In summary, overexpression of miR‐34a‐5p inhibited the expression of SIRT1 and increased the expression or release of IL‐1β/COX2/PEG2, which further enhanced the release of CGRP, thereby triggering the pain during migraine onset." (PMID 33155431, 2021). "Therefore, our hypothesis was that overexpression of miR‐34a‐5p may inhibit the expression of SIRT1 and up‐regulation of IL‐1β/COX2/PEG2, thereby triggering the release of CGRP to induce the pain during migraine." (PMID 33155431, 2021).
mixed phenotype acute leukemia (3 papers, 2022 to 2023). An acute leukemia of ambiguous lineage. "Another recent study found that SIRT1 knockout can prevent age-dependent mixed phenotype acute leukemia (MPAL) and HSC aging, suggesting a potential future avenue for treating MPAL and modifying the functions of aging HSCs." (PMID 37065445, 2023). "The majority of secondary and tertiary BMT recipients of aging wild type donor cells developed B/myeloid mixed phenotype acute leukemia (MPAL), which was markedly inhibited by Sirt1 knockout." (PMID 35484199, 2022).
myelodysplastic syndrome (3 papers, 2019 to 2022). A clonal hematopoietic disorder characterized by dysplasia and ineffective hematopoiesis in one or more of the hematopoietic cell lines. "The authors found that SIRT1 levels, and hence TET2 activity, were decreased in aberrant HSPCs in myelodysplastic syndrome (MDS), whereas overexpression of SIRT1 or its activation by agonist SRT1720 resulted in reduced myelodysplastic HSC survival." (PMID 33114351, 2020).